HSD11B1 (hydroxysteroid 11-beta dehydrogenase 1)
Diseases named in the same sentence as HSD11B1 in open-access papers (continued):
Sharing a sentence is not in itself a finding about the gene and the disease.
cutaneous melanoma (2 papers, 2022 to 2023). A primary melanoma arising from atypical melanocytes in the skin. "Review of cancer genomics data sets available via the cBioPortal for Cancer Genomics reveals amplification of HSD11B1 expression in 8–10% of breast and hepatobiliary cancer studies, while around 8% of cutaneous melanomas show either mutation (4%) or amplification (4%) of the gene." (PMID 36940215, 2023). "The three CCP-related gene signatures–HSD11B1, NDRG1 and CDCA3–may each independently predict the clinical outcomes of cutaneous melanoma patients, according to our prognostic study (both in OS and DSS)." (PMID 36713580, 2022).
endometriosis (2 papers, 2024 to 2025). The growth of functional endometrial tissue in anatomic sites outside the uterine body. "Indicative of a higher state of cellular stress, we also found that the decidualizing cells of donors with endometriosis displayed higher expression of stress response genes, such as CRYAB, HSD11B1 and GLRX." (PMID 38402336, 2024).
gastrointestinal stromal tumor (2 papers, 2019 to 2024). "HSD11B1 exhibits oncogenic potential in primary imatinib-naïve gastrointestinal stromal tumors driven by HSD11B1 copy-number gain or missense mutations." (PMID 31886185, 2019).
Glucose intolerance (2 papers, 2017 to 2024). Glucose intolerance (GI) can be defined as dysglycemia that comprises both prediabetes and diabetes. "Finally, overexpression of Hsd11b1 is reported to offer some protection against high-fat diet-induced glucose intolerance, through increasing both islet mass and function." (PMID 28443133, 2017).
heart failure (2 papers, 2016 to 2017). Inability of the heart to pump blood at an adequate rate to meet tissue metabolic requirements. "This is consistent with our previous observations that Hsd11b1 deletion in these cells did not influence angiogenesis or the development of heart failure following MI." (PMID 28522730, 2017).
Hepatic steatosis (2 papers, 2019 to 2022). Steatosis is a term used to denote lipid accumulation within hepatocytes. "Other studies, in which mice had been given corticosterone when Hsd11b1 (the enzyme responsible for the regeneration of corticosterone) had been deleted, had identified glucocorticoid regeneration in adipose tissue as a key factor in corticosterone-induced hepatic steatosis and fatty acid excess." (PMID 30794724, 2019).
hepatoma (2 papers, 2019 to 2024). "However, considering the lack of expression of HSD11B1 and CBR1 in human hepatoma cells, the potential contribution of these enzymes in cortisone metabolism, resulting in differences in the proportion of the 5β-reduced product, may be small, but cannot be excluded." (PMID 31330134, 2019).
Impaired glucose tolerance (2 papers, 2015 to 2020). An abnormal resistance to glucose, i.e., a reduction in the ability to maintain glucose levels in the blood stream within normal limits following oral or intravenous administration of glucose. "Additionally, two studies have shown that HSD11B1 expression in abdominal SAT is greater in those with impaired glucose tolerance and T2DM compared with normal controls." (PMID 26056536, 2015).
liver fibrosis (2 papers, 2018 to 2022). "In contrast, a specific HSD11B1 inhibitor worsens liver fibrosis in mice." (PMID 35614477, 2022).
prostate carcinoma (2 papers, 2015). A carcinoma that arises from epithelial cells of the prostate gland. "Hsd11b1 is present in PC3 and LnCaP human prostate cancer cells, and the HSD11B1’s 11-dehydrogenase activity is preserved while the 11-reductase activity is not, indicating HSD11B1 is important for maintaining the concentration of glucocorticoid in prostate and prostate cancer cells." (PMID 26710108, 2015).
psoriasis (2 papers, 2020 to 2024). An autoimmune condition characterized by red, well-delineated plaques with silvery scales that are usually on the extensor surfaces and scalp. "recognized estrogen receptor 1 (ESR1), opioid receptor mu 1 (OPRM1), and hydroxysteroid 11-beta dehydrogenase 1 (HSD11B1) as promising therapeutic targets for psoriasis." (PMID 39883516, 2024). "Therefore, HSD11B1 might be recognized as the probable gene associated with psoriasis." (PMID 32669126, 2020). "Thus, HSD11B1 was connected with psoriasis which has been always recognized as a chronic inflammatory disease of the skin." (PMID 32669126, 2020). "Besides, some psoriasis-related genes such as SPRR genes, HSD11B1, GGH, CXCR2, IVL, OASL, ISG15, and CXCL10 may be important targets in psoriatic therapy." (PMID 32669126, 2020).
Sepsis (2 papers, 2021 to 2023). Sepsis is defined as life-threatening organ dysfunction caused by a dysregulated host response to infection. "11β-hydroxysteroid dehydrogenase type 1 (11β-HSD1), encoded by Hsd11b1, is a reductase that can convert inactive cortisone into metabolically active cortisol, but the role of 11β-HSD1 in sepsis-induced myocardial dysfunction remains poorly understood." (PMID 37246430, 2023).
skin cancer (2 papers, 2025 to 2026). "In skin cancer diagnosis, HSD11B1, SLC45A2, and KRT20 have also been demonstrated to play key roles." (PMID 40917881, 2025).
acne (1 paper, 2021). An inflammatory process of the sebaceous glands which is characterized by comedones, nodules, papules and/or pustules on the skin. "In contrast, a study in Egypt found that HSD11B1 rs12086634 variants were associated with acne risk while the relationship between HSD11B1 rs846910 variants and acne risk was unclear." (PMID 33849530, 2021).
cardiac hypertrophy (1 paper, 2018). "However, in mice in which cardiac hypertrophy was induced by infusion of either Iso or AngII, Hsd11b1 expression was reduced." (PMID 30338214, 2018).
corticotroph adenomas (1 paper, 2015). "Expression of both HSD11B1 and HSD11B2 have been documented in healthy dogs, and abnormal HSD11B1 and HSD11B2 expression patterns were found in canine corticotroph adenomas." (PMID 26262685, 2015).
dementia (1 paper, 2024). Loss of intellectual abilities interfering with an individual's social and occupational functions. "The data suggest that an age-related increase in the expression of hippocampal HSD11B1 is likely to raise cortisol concentrations in this cognitive brain area, and thereby contribute to the etiology of neuropathologies that ultimately lead to neuronal loss and dementia." (PMID 38560025, 2024).
dermatitis (1 paper, 2018). An inflammatory process affecting the skin. "Laminin subunit beta 3 (LAMB3) and hydroxysteroid 11-beta dehydrogenase 1 (HSD11B1) genes, which influence hair morphogenesis and dermatitis in both mice and humans, respectively, were identified as the most likely candidates for influencing mature fleece weight within the associated QTL." (PMID 29670642, 2018).
endometrial tumors (1 paper, 2024). "We found that endometrial tumors of both low- and high-grade have significantly higher HSD11B2 levels than tumor-adjacent endometrium, which, like the control cell line HIEEC, displayed low HSD11B2/HSD11B1 ratio compared to EC of any grade." (PMID 39205690, 2024).
esophageal cancer (1 paper, 2023). A primary or metastatic malignant neoplasm involving the esophagus. "Importantly, HSD11B1 but not CYP11B1 expression was upregulated in cancer compared with matched healthy control tissues in a range of human tumors including lymphomas (B cell and T cell) and pancreatic, colorectal, stomach, and esophageal cancers." (PMID 37471141, 2023).
Hepatitis (1 paper, 2024). Inflammation of the liver. "Macromolecular target prediction using the SwissTargetPrediction indicated that these molecules could also target enzymes associated with metabolic diseases (HSD11B1), could be aromatase inhibitors (CYP19A1), and exhibited anti-hepatitis and antihyperthyroidism (SHBG) activities, among others." (PMID 38675469, 2024).
Hyperkalemia (1 paper, 2016). An abnormally increased potassium concentration in the blood. "As the present data show that the effects of Hsd11b1 gene targeting are cardiomyocyte independent, 11β-HSD1 inhibitors may offer additional benefits in patients already receiving MR antagonist therapy or an alternative in patients for whom hyperkalemia precludes the use of MR antagonists." (PMID 26465199, 2016).
infiltrating ductal carcinoma (1 paper, 2022). "However, except for HSD11B1 and SH2D2A in infiltrating ductal carcinoma, other MDGs did not have statistically significant clinical outcome, possibly due to small sample size." (PMID 35844785, 2022).
leiomyoma (1 paper, 2025). A well-circumscribed benign smooth muscle neoplasm characterized by the presence of spindle cells with cigar-shaped nuclei, interlacing fascicles, and a whorled pattern. "DEX treatment increased HSD11B1 transcription in normal myometrial and human endometrial stromal cell cultures, but to a significantly greater extent in leiomyoma (P < .001)." (PMID 40290045, 2025). "HSD11B1 mRNA and protein levels in leiomyoma, paired myometrium, and normal myometrium." (PMID 40290045, 2025). "Similarly, DEX increased HSD11B1 mRNA levels by 4-fold in normal myometrial cells and by 3.2-fold in HESCs; however, these increases were significantly lower than the 9.4-fold upregulation observed in leiomyoma cells (P < .05)." (PMID 40290045, 2025). "However, in FKBP5 siRNA-transfected leiomyoma cells, DEX treatment produced a lesser (2.5-fold) increase in HSD11B1 levels compared to control (P < .05)." (PMID 40290045, 2025). "Notably, this enhanced HSD11B1 expression in leiomyoma was absent following FKBP5 knockdown, highlighting the interconnectivity between FKBP5 and HSD11B1 in inducing a myofibroblast phenotype." (PMID 40290045, 2025).
liver cancer (1 paper, 2018). An epithelial or non-epithelial malignant neoplasm that arises from the liver. "Interestingly, loss of HSD11B1 expression has been reported to enhance glycolysis in liver cancer." (PMID 29162555, 2018).
muscular atrophy (1 paper, 2020). The loss of muscle tissue due to inactivity or disease. "Our observations confirm the previously published data, which clearly shows that HSD11B1 may be a major regulator of the muscular atrophy." (PMID 32316389, 2020).
myocardial infarct (1 paper, 2017). "However, Col1a2 Cre has recently been applied successfully to target fibroblasts during myocardial infarct healing, and in future, this approach will provide a means for testing the importance of Hsd11b1 in fibroblasts, and other mesenchymal cells, post MI." (PMID 28522730, 2017).
osteoarthritis (1 paper, 2025). A noninflammatory degenerative joint disease occurring chiefly in older persons, characterized by degeneration of the articular cartilage, hypertrophy of bone at the margins and changes in the synovial membrane. "A subsequent comparative analysis parallels these 9 pivotal osteoarthritis-associated genes with 3 previously identified chondrocyte-specific targets—namely, Mmp2, Hsd11b1, and Pla2g2a—revealed substantial overlap with Pla2g2a." (PMID 40880649, 2025).
peritonitis (1 paper, 2023). Inflammation of the peritoneum (tissue that lines the abdominal wall and covers most of the organs in the abdomen). "For example, it has been shown that neutrophils upregulate Hsd11b1 expression at early stages of acute peritonitis, potentially limiting inflammation." (PMID 37936704, 2023).
pituitary adenomas (1 paper, 2019). "Whilst the major glucocorticoid metabolising enzymes, 11β-hydroxysteroid dehydrogenase (11βHSD; HSD11B1 and HSD11B2), have been described in human pituitary adenomas, the activity of these enzymes within different pituitary cell types has not been reported." (PMID 31717753, 2019).
polyarthritis (1 paper, 2025). "Moreover, HH pigs had upregulated HSD11B1, which could be a local anti-inflammatory regulation via the re-activation of cortisone to cortisol and glucocorticoid signaling as described in murine models of polyarthritis." (PMID 40159791, 2025).
preeclampsia (1 paper, 2024). Preeclampsia is a hypertensive disorder of pregnancy that is characterized by new-onset hypertension with proteinuria presenting after 20 weeks of gestation, and depending on mild or severe forms may initially present with severe headache, visual disturbances, and hyperreflexia. "In the preeclampsia group, the mRNA expression of only one enzyme, namely HSD11B1, was directly proportional to its precursor-to-product ratio in serum." (PMID 39684415, 2024). "We identified CYP17A1, HSD17B3, SRD5A1, CYP19A1, CYP11B1, HSD11B1 and HSD11B2 as potentially affected enzymes in preeclampsia." (PMID 39684415, 2024).
renal carcinoma (1 paper, 2024). A carcinoma arising from the epithelium of the renal parenchyma or the renal pelvis. "Our results shed light on the inhibitory function of glucocorticoid regeneration through HSD11B1 in the immune response against renal cancer." (PMID 38170044, 2024). "Among all the cancer types available in the TCGA database, the poor prognostic value of intratumoral HSD11B1 expression was seen mainly in patients with renal cancer." (PMID 38170044, 2024). "In a subcutaneous mouse model of renal cancer, the combination of an HSD11B1 inhibitor with anti-PD-1 treatment increased the proportion of tumor-infiltrating dendritic cells." (PMID 38170044, 2024). "In conclusion, these results support the use of HSD11B1 inhibitors to improve the outcome of immunotherapy in renal cancer and highlight the role of the endogenous glucocorticoid metabolism in the efficacy of immunotherapy." (PMID 38170044, 2024). "Among the 39 cancer subtypes tested in TCGA, the expression of HSD11B1 was found to correlate with a poor prognosis only in stomach adenocarcinoma and renal cancer." (PMID 38170044, 2024). "As HSD11B2 provides the substrates for HSD11B1 and higher levels of HSD11B2 activity have been described in the kidney compared to other tissues, we hypothesized that the inhibition of HSD11B1 could be more impactful in an orthotopic model of renal cancer." (PMID 38170044, 2024). "In conclusion, this work supports the hypothesis that the combination of an HSD11B1 inhibitor with immune checkpoint blockade may be beneficial in renal cancer patients, highlighting the role of endogenous glucocorticoid metabolism in the efficacy of immunotherapy." (PMID 38170044, 2024). "In order to better characterize the effect of HSD11B1 inhibition on the antitumor immune response in the context of TLR7 stimulation, we tested the impact of HSD11B1 activity on the capacity of mouse dendritic cells to initiate an antitumor immune response against renal cancer cells." (PMID 38170044, 2024).
schizophrenia (1 paper, 2024). A major psychotic disorder characterized by abnormalities in the perception or expression of reality. "Integrating HC ELEs with GWAS and gene regulatory networks further helps pinpoint previously undescribed but functionally relevant genes for BMI (e.g., CDK5, HSD11B1) and schizophrenia (e.g., HYLS1, PMM2)." (PMID 38167462, 2024).
Skeletal myopathy (1 paper, 2023). "In mice, selective removal of HSD11B1 prevented skeletal myopathy by reducing the availability of GCs." (PMID 37943405, 2023).
skin aging (1 paper, 2022). The gradual irreversible changes in structure of skin that occur as a result of the passage of time.. "HSD11B1 is an enzyme that activates GCs and has been reported as a critical driver of skin aging." (PMID 36551249, 2022).
skin atrophy (1 paper, 2018). The degeneration and thinning of the epidermis and dermis. "Supporting this, aged mice treated with HSD11B1 inhibitors or aged HSD11B1 KO mice featured improvements in skin atrophy and cutaneous healing." (PMID 29966221, 2018).
squamous cell lung carcinoma (1 paper, 2023). A carcinoma arising from squamous bronchial epithelial cells. "Parallel to our findings in mouse tumor cell lines, HSD11B1 was expressed at low levels in squamous cell lung cancer." (PMID 37471141, 2023).
vitamin A deficiency (1 paper, 2019). Deficiency of vitamin A due to malnutrition, malabsorption, or dietary lack. "There are however changes in the hippocampus with vitamin A deficiency, inducing decline in the genes for MR and GR and decrease in Hsd11b1, all of which are restored by RA treatment." (PMID 31736706, 2019).